MALAT1 (metastasis associated lung adenocarcinoma transcript 1)
Diseases named in the same sentence as MALAT1 in open-access papers (continued):
Sharing a sentence is not in itself a finding about the gene and the disease.
pancreatic cancer (continued). "The main findings of the study were as follows: MALAT1 promotes oncogenesis and enhances KRAS/mitogen-activated protein kinase (MAPK) signalling pathway activation in pancreatic cancer at least in part through a direct interaction with miR-217." (PMID 28701723, 2017). "However, the role of EZH2 in pancreatic cancer and its interaction with MALAT-1 remain unclear." (PMID 26848980, 2016). "In the present study, we revealed that MALAT-1 could increase the proportion of pancreatic CSCs, maintain self-renewing capacity, decrease the chemosensitivity to anticancer drugs, and accelerate tumor angiogenesis in vitro, and promote tumorigenicity of pancreatic cancer cells in vivo." (PMID 25811929, 2015). "Similar to MALAT1, an increased expression of HOX antisense intergenic RNA HOTAIR has been found in pancreatic tumors." (PMID 25910082, 2015). "Pancreatic cancer cell lines AsPC-1/M-si1 and CFPAC-1/M-si1, which stably knock down expression levels of MALAT-1, as well as that of controls (AsPC-1/M-nc and CFPAC-1/M-nc) have been established in our previously study." (PMID 25811929, 2015). "We therefore investigated the impact of candidate drugs gemcitabine, a commonly used anti-cancer agent against pancreatic carcinoma in clinic, on the cell proliferation, and calculated the 50% inhibitory drug concentration (IC50) following MALAT-1 knockdown." (PMID 25811929, 2015). "Also, increasing the amount of PVT1 with MALAT1 and HOTTIP in serum has been suggested to predict the effect of gemcitabine in pancreatic cancer." (PMID 38559560, 2024). "Additionally, MALAT-1 knockdown drastically decreased LC3 degradation and colocalization in pancreatic cancer cells." (PMID 38511067, 2024). "MALAT1 knockdown in pancreatic cancer cells inhibited the sphere formation and the expression of self-renewal factors, including SOX2 and CD133, implying that MALAT1 may increase pancreatic CSC stemness characteristics by upregulating SOX2 expression." (PMID 39170516, 2024). "Indeed, upregulation of METTL3 increased the MALAT1 level, and downregulation of METTL3 reduced the expression of MALAT1 in pancreatic cancer cells." (PMID 36212476, 2022). "MALAT-1 could also exert its oncogenic effects through mediation of EZH2, miR-216a, miR-217, miR-200c, or Hippo-YAP signaling in pancreatic cancers." (PMID 34439315, 2021). "Based on our current data and previous studies, we hypothesize that KrasG12D, PI3K, ERK, JNK, p38MAPK, vimentin, lncRNA MALAT1, lncRNA SNHG1, and lncRNA RP11-363N22.3 targeted by hsa-miR-143-3p may play crucial roles in pancreatic cancer." (PMID 33643376, 2021). "RUNX1-IT1, ENSG00000254041.1, MALAT1, LOC285194, LncRNA-UFC1, RP11-263F15.1, BC008363, MEG3, and HULC are among lncRNAs whose expressions have been correlated with the survival of patients with pancreatic cancer." (PMID 34827663, 2021). "For further expounding the molecular mechanism of IPO7 in regulating pancreatic cancer progression, StarBase and DIANA LncBase Predicted v.2 were performed to explore the miRNAs that potentially interacted with MALAT1, and miR-129-5p was among the candidate miRNAs." (PMID 34660566, 2021). "From reviewing previous studies, miR-29b-2-5p is reported to target CBI-b to inhibit the proliferation of pancreatic cancer cells, and miR-101-3p could hinder the growth and metastasis of NSCLC through attenuating MALAT-1 mediated PI3K/AKT signal pathway." (PMID 33612479, 2021). "Previous studies showed that MALAT-1 is overexpressed in pancreatic cancer cell lines and tumors compared to non-transformed pancreatic cells/tissue." (PMID 29389953, 2018).
pancreatic cancer (continued). "Analysis of changes in gene expression after MALAT-1 knockdown shows that this lncRNA represses several tumor suppressor-like genes including N-myc downregulated gene-1 (NDRG-1), a tumor suppressor in pancreatic cancer that is also corepressed by EZH2 (a PRC2 complex member)." (PMID 29389953, 2018). "This is the first evidence of MALAT1 expression in FFPE patient tissues of breast, colorectal and pancreatic cancers by chromogenic staining, suggesting that lncRNA MALAT1 is associated with multiple cancers and its use as a therapeutic target should be investigated further." (PMID 30189670, 2018). "HOTAIR, PVT-1, MALAT-1, and GAS5 are some of most widely studied lncRNAs in pancreatic cancer." (PMID 27689078, 2016). "Furthermore, lncRNAs MALAT1, SNHG1, and RP11-363N22.3 may also play a role in pancreatic cancer via hsa-miR-143-3p." (PMID 33643376, 2021). "While miR-200c-3p and miR-217 induce MALAT1 RNA degradation, MALAT1 suppresses miR-200c-3p and miR-217 function and miR-217 translocation from the nucleus to the cytoplasm, up-regulates ZEB1 and KRAS expression, and induces pancreatic cancer cell migration and invasion." (PMID 32174966, 2020). "However, whether an interaction involving miR-217, MALAT1 and KRAS occurs in pancreatic cancer remains unknown." (PMID 28701723, 2017). "Furthermore, we noted the existence of a negative correlation between MALAT1 and miR-217 expression in pancreatic tumour specimens and cell lines." (PMID 28701723, 2017). "MALAT-1 expression in many tumors is a negative prognostic factor for patients, and results obtained in this study and previous reports confirm that MALAT-1 is a pro-oncogenic factor for pancreatic cancer." (PMID 29389953, 2018).
liver cancer (67 papers, 2013 to 2025). An epithelial or non-epithelial malignant neoplasm that arises from the liver. "On the other hand, MALAT1 in liver cancer has been linked to the promotion of tumor development via a variety of mechanisms, including angiogenesis and cell cycle modulation." (PMID 39325172, 2024). "Additionally, MALAT1 overexpression has been associated with metastasis in lung, breast and liver cancers." (PMID 32503170, 2020). "Using the University of California Santa Cruz (UCSC) Xena platform, we examined likely association or correlation between MALAT1 expression and the sample types, histological types, and histological grade (cellular differentiation status) of samples in the TCGA Liver cancer (LIHC) cohort (n = 438)." (PMID 32326045, 2020). "While Cy5.5-labeled MALAT1-ASOs demonstrated excellent imaging effects in liver cancer, their potential application in other tumors requires further validation." (PMID 40597438, 2025). "Overall, our results indicated that miR-423-5p in liver cancer has promising translational value, thanks to its capability to interfere with MALAT-1 and its pro-tumorigenic role." (PMID 41029313, 2025). "Given this background, our current study takes a close look at how miR-423-5p and MALAT-1 work together in liver cancer, focusing specifically on how they influence tumor functionality and mitochondrial metabolism." (PMID 41029313, 2025). "The expression of miRNA-613 was markedly upregulated, and the capacity of liver cancer cells to invade was dramatically reduced in liver cancer cells with lncRNA MALAT-1 knockdown." (PMID 38511067, 2024). "Several lncRNAs were reported to have an important role in tumorigenesis and metastasis of HCC as highly upregulated in liver cancer (HULC), metastasis-associated lung adenocarcinoma transcript 1 (MALAT1) and HOX antisense intergenic RNA (HOTAIR)." (PMID 37888208, 2023). "Subsequently, we found that MALAT1-associated methylation was associated with poor survival of HCC patients and was enriched for terms associated with liver cancer progression." (PMID 36685103, 2022). "The area under the curve was 0.821, P = 0.004, which was statistically significant, indicating that lncRNA MALAT1 was significant in the diagnosis of liver cancer." (PMID 35706002, 2022). "It is suggested that in liver cancer cells, lncRNA MALAT1 can inhibit the expression of miRNA-613 and promote the invasion and metastasis of liver cancer cells through peripheral blood vessels." (PMID 35706002, 2022). "lncRNA MALAT1 was knocked down in liver cancer cells, and the expression of miRNA-613 in liver cancer cells was detected by q-PCR." (PMID 35706002, 2022). "MALAT1 plays a regulatory role in liver diseases, including hepatic fibrosis, liver regeneration, liver cancer, and fatty liver diseases." (PMID 35145971, 2021). "MALAT1 expression has been revealed to be increased in cancer spheroids compared with parental liver cancer cells." (PMID 34368145, 2021). "MALAT1 silencing has decreased sphere construction and reduced expression of stem cell markers in liver cancer cells." (PMID 34368145, 2021). "We also showed that the LncRNA MALAT1 overexpression in liver cancer positively correlates with poor cellular differentiation status and disease progression." (PMID 32326045, 2020). "According to literature survey, many DE lncRNAs, such as MALAT1, CDKN2B-AS1, and HOTTIP, have been reported to be associated with liver cancers." (PMID 32760422, 2020). "In liver cancer cell lines (HepG2 and Hep3B), MALAT-1 regulates cancer-related microRNAs (miRNAs), such as mir-574 and mir-20b, contributing to potential targets (such as RAS and MAPK) and Wnt/β-catenin signaling pathway, thus promoting HCC development." (PMID 31350456, 2019). "A study of whole-genome mutational landscape of liver cancer also discovered mutations in lncRNA NEAT1 and MALAT1." (PMID 31338259, 2019).
liver cancer (continued). "In summary, our study provides a promising evidence that MALAT1 can be used to predict poor clinical features and prognosis in patients with liver cancer." (PMID 31466138, 2019). "Next, we altered the expression of MALAT1 in HepG2 and Huh‐7 cells to investigate the biological role of MALAT1 in liver cancer." (PMID 31466138, 2019). "The metastasis-associated lung adenocarcinoma transcript 1 (Malat1) is over-expressed in several disease states and YAP was found to upregulate Malat1 in liver cancer, whereas SRSF1 was found to have an opposing effect." (PMID 29534050, 2018). "Some evidence has also been reported suggesting that HULC can also act to inhibit c-Myc expression and PI3K/Akt signalling, and HULC has also been shown to cooperate with MALAT1 to promote liver cancer stem cell growth/aggressiveness." (PMID 29701689, 2018). "A more recent study demonstrated that MALAT-1, with another lncRNA highly upregulated in liver cancer (HULC), increased the expression of telomere repeat-binding factor 2 (TRF2) and accelerated liver cancer stem cell growth." (PMID 28951743, 2017). "HULC overexpression, MALAT1 overexpression, HULC overexpression plus MALAT1 overexpression promoted liver cancer stem cell cell proliferation compared to control (t-test, P < 0.01)." (PMID 27782152, 2016). "YAP1 up-regulates MALAT1 expression in liver cancer, whereas serine/arginine-rich splicing factor 1 (SRSF1) played an opposing role." (PMID 27835600, 2016). "In this report, we focused mainly on the view how HULC plus MALAT1 functions during liver cancer stem cells malignant growth." (PMID 27782152, 2016). "Intriguingly, MALAT1 combined with HULC resulted in the greater efficiency in stable liver cancer stem cell lines transfected with pCMV6-A-GFP, pCMV6-A-GFP-HULC, pCMV6-A-GFP-MALAT1, pCMV6-A-GFP-HULC plus pCMV6-A-GFP-MALAT1." (PMID 27782152, 2016). "Intriguingly, MALAT1 combined with HULC resulted in the greater effeciency in stable liver cancer stem cell lines transfected pCMV6-A-GFP, pCMV6-A-GFP-HULC, pCMV6-A-GFP-MALAT1, pCMV6-A-GFP-HULC plus pCMV6-A-GFP-MALAT1 (upper)." (PMID 27782152, 2016). "Intriguingly, MALAT1 combined with HULC resulted in the greater effeciency in stable liver cancer stem cell lines transfected pCMV6-A-GFP, pCMV6-A-GFP-HULC, pCMV6-A-GFP-MALAT1, pCMV6-A-GFP-HULC plus pCMV6-A-GFP-MALAT1." (PMID 27782152, 2016). "Collectively, TRF2 knockdown abrogated the oncogenic function of the MALAT1 plus HULC in liver cancer cells." (PMID 27782152, 2016). "The soft-agar colony-formation rates were added up to 55.7%, 59.9%, 91.5% in HULC, MALAT1, HULC plus MALAT1 overexpressed liver cancer stem cells, as well as the soft-agar colony-formation rate was 30.8% in control (t-test, P < 0.01)." (PMID 27782152, 2016). "The transwell cells positive rates were added up to 38.5%, 41.5%, 69.8% in HULC, MALAT1, HULC plus MALAT1 overexpressed liver cancer stem cells, as well as the transwell cells positive rate was 16.5% in control (t-test, P < 0.01)." (PMID 27782152, 2016). "In summary, our present data indicated that HULC combined with MALAT1 promotes liver cancer stem cells malignant progression through altering telomere and MSI, with diagnostic and prognostic implications." (PMID 27782152, 2016). "Together, these results suggest that HULC and MALAT1 accelerates the liver cancer stem cells proliferation." (PMID 27782152, 2016). "It is worth noting that our findings in this study provide novel evidence for an active role of HULC plus MALAT1 promotion of liver cancer stem cell growth." (PMID 27782152, 2016). "Our demonstrations suggest that haploinsufficiency of HULC/MALAT1 plays an important role in malignant growth of liver cancer stem cell." (PMID 27782152, 2016). "Collectively, these findings demonstrate that HULC and/or MALAT1 enhances liver cancer stem cells’ progression in vivo." (PMID 27782152, 2016).
liver cancer (continued). "Metastasis associated lung adenocarcinoma transcript 1 (MALAT1) was found to be over expressed not only in breast, pancreas, colon, prostate, and liver cancers, but also in early-stage metastasizing NSCLC." (PMID 26052251, 2015). "Several important lncRNAs are reported to induce EMT, including highly upregulated in liver cancer (HULC), metastasis-associated lung adenocarcinoma transcript 1 (MALAT-1), H19, and HOX transcript antisense intergenic RNA (HOTAIR)." (PMID 24598126, 2014). "The lncRNAs of interest for this test—namely ANRIL, H19, HOTAIR, HULC, MALAT1, WISPER, and ZFAS1—were initially identified in other pathologies, as evident in some of their names, highly upregulated in liver cancer (HULC), or metastasis associated lung adenocarcinoma transcript 1 (MALAT1)." (PMID 40271126, 2025). "The potential mechanisms underlying the relationship between MALAT1 and HCC prognosis were studied using combined data from RNA sequencing, DNA methylation, and somatic mutation data from The Cancer Genome Atlas (TCGA) liver cancer cohort." (PMID 36685103, 2022). "Our work showed that the lncRNA MALAT1 is overexpressed in liver cancer tissues and cell lines." (PMID 32326045, 2020). "Moreover, another study found that HULC cooperates with MALAT1 to aggravate the growth of liver cancer stem cells." (PMID 31636654, 2019). "Our study also demonstrated that other SNPs were correlated with overall cancer risk, namely, metastasis-associated lung adenocarcinoma transcript 1 (MALAT1, rs619586 A/G), HOXA distal transcript antisense RNA (HOTTIP, rs1859168 A/C), and highly up-regulated in liver cancer (HULC, rs7763881 A/C)." (PMID 29802154, 2018). "There are numerous in vitro studies claiming a role for Malat1 in liver cancer progression." (PMID 29467431, 2018). "A recent report has shown that HULC affects the stemness of HCC cells by cooperating with MALAT-1, contributing to the promotion of liver cancer stem generation through binding and loading on the promoter region of telomere repeat-binding factor 2 (TRF2) to enhance telomerase activity." (PMID 28872613, 2017). "The findings suggest that HULC, in combination with MALAT1, may contribute significantly to malignant growth of liver cancer stem cells through metabolism regulation." (PMID 28872613, 2017). "HULC plus MALAT1 showed a strong function in the liver cancer stem cell growth." (PMID 27782152, 2016). "Furthermore, HULC, MALAT1 overexpression promotes the growth of liver cancer stem cells in vitro and in vivo." (PMID 27782152, 2016). "The expression of MALAT1 in five cell lines derived from liver cancer cells was also examined." (PMID 26735578, 2016). "Furthermore, we detected the S phase cells by BrdU staining in HULC or MALAT1 overexpressed liver cancer stem cells." (PMID 27782152, 2016). "HULC was significantly overexpressed in pCMV6-A-GFP-HULC, pCMV6-A-GFP-HULC plus pCMV6-A-GFP-MALAT1 transfected liver cancer stem cells compared the control, and MALAT1 were significantly overexpressed in pCMV6-A-GFP-MALAT1, pCMV6-A-GFP-HULC plus pCMV6-A-GFP-MALAT1 transfected liver cancer stem cell." (PMID 27782152, 2016). "However, this action was fully abrogated in liver cancer stem cell lines transfected with pCMV6-A-GFP-HULC plus pCMV6-A-GFP-MALAT1 plus pFGP-V-RS—TRF2 or pGFP-V-RS-GFP-HULC plus pGFP-V-RS –MALAT1 plus pcDNA-CREPT (30.56%, 33.24% vs 36.7%, respectively, t-test, P < 0.01)." (PMID 27782152, 2016). "However, this action was fully abolished in liver cancer stem cell lines transfected with pCMV6-A-GFP-HULC plus pCMV6-A-GFP-MALAT1 plus pFGP-V-RS—TRF2 or pGFP-V-RS-GFP-HULC plus pGFP-V-RS –MALAT1 plus pcDNA-CREPT (9.7days, 9.5 days vs 10.2 days, respectively, t-test, P < 0.01)." (PMID 27782152, 2016).